LIMCH1 (LIM and calponin homology domains 1)
Description:
Actin stress fibers-associated protein that activates non-muscle myosin IIa. Activates the non-muscle myosin IIa complex by promoting the phosphorylation of its regulatory subunit MRLC/MYL9. Through the activation of non-muscle myosin IIa, positively regulates actin stress fibers assembly and stabilizes focal adhesions. It therefore negatively regulates cell spreading and cell migration.
Synonyms: DKFZP686A01247; LIMCH1A; LMO7B
Tractability: PROTAC: ubiquitination databases record sites on it; its protein half-life has been measured.
Gene: Protein-coding gene on chromosome 4 (41,359,574 to 41,700,049, forward strand). Ensembl gene ENSG00000064042.
Subcellular location: Cytoplasm, cytoskeleton, stress fiber
Subcellular location (Human Protein Atlas): Actin filaments
Gene Ontology:
Molecular function: myosin II head/neck binding; protein binding; actin binding
Biological process: cytoplasmic actin-based contraction involved in cell motility; negative regulation of cell migration; positive regulation of protein phosphorylation; positive regulation of stress fiber assembly; regulation of focal adhesion assembly; actomyosin structure organization
Cellular component: actin cytoskeleton; myosin II complex; stress fiber
Genetic constraint (gnomAD): Loss-of-function variants: 90 observed, 139.69 expected, observed/expected ratio (o/e) 0.64, 90% interval 0.54 to 0.77. The upper end of that interval is the gene's LOEUF score, 0.77, which puts it in group 3 of 6, group 1 being the genes least tolerant of losing a copy. Missense variants: 1,429 observed, 1,631.6 expected, observed/expected ratio (o/e) 0.88, 90% interval 0.84 to 0.92. Synonymous variants: 538 observed, 593.89 expected, observed/expected ratio (o/e) 0.91, 90% interval 0.84 to 0.97.
Homologues: Orthologues: chimpanzee LIMCH1 (99% identical), macaque LIMCH1 (96% identical), pig LIMCH1 (85% identical), rabbit LIMCH1 (82% identical), rat Limch1 (74% identical), mouse Limch1 (72% identical), guinea pig LIMCH1 (53% identical), tropical clawed frog limch1 (50% identical), zebrafish limch1b (27% identical), zebrafish limch1a (26% identical), Caenorhabditis elegans lim-8 (11% identical). Paralogues in human: LMO7 (23% identical).
Diseases named in the same sentence as LIMCH1 in open-access papers:
LIMCH1 is named in the same sentence as 26 diseases in open-access papers, as found by Europe PMC text mining. Sharing a sentence is not in itself a finding about the gene and the disease. The quoted sentences say what the papers report.
cervical cancer (7 papers, 2021 to 2023). A primary or metastatic malignant neoplasm involving the cervix. "LIMCH1 is upregulated with a strong association to poor prognoses, representing a potential biomarker for cervical cancer treatment." (PMID 35565241, 2022). "Several reports have linked LIMCH1 depletion to cancer progression, suggesting reduced LIMCH1 levels may serve as a biomarker for tumor growth and metastasis in lung, breast, and cervical cancers." (PMID 36977593, 2023). "Moreover, LIMCH1 was identified as a gene signature with high prognostic power in aggressive cervical cancer." (PMID 36338962, 2022). "HLA-DQB1 and LIMCH1 are potential biomarkers guiding cervical cancer treatment." (PMID 33723390, 2021). "LIMCH1 was recently identified as a biomarker for aggressive cervical cancer." (PMID 34885095, 2021). "Two of the signature genes, HLA-DQB1 and LIMCH1, displayed independent prognostic significance when investigated in a large population-based patient cohort by IHC, indicating a promising role as prognostic biomarkers guiding cervical cancer treatment." (PMID 33723390, 2021). "However, whether LIMCH1 plays a role in translation and whether this can be exploited in cervical cancer treatment needs to be determined." (PMID 33723390, 2021). "This may suggest that LIMCH1 is involved in regulating translational processes in cervical cancer." (PMID 33723390, 2021). "Two genes within the 10-gene signature (LIMCH1 and HLA-DQB1) were selected for further analyses as potential prognostic markers in a large population-based cervical cancer cohort by IHC performed in TMAs." (PMID 33723390, 2021).
breast carcinoma (5 papers, 2010 to 2023). "There is an unfavorable association between LIMCH1 protein expression and distant metastasis-free survival in breast cancer." (PMID 37965478, 2023). "Several recent studies reported that LIMCH1 expression was associated with breast cancer, clear cell renal cell carcinoma, and lung cancer." (PMID 33391414, 2021). "Both KLK6 and LIMCH1 expression has been linked to clinical outcome of breast cancer patients." (PMID 38036593, 2023). "We observed over-expression of LIMCH1, a gene encoding zinc-binding protein, and also four genes encoding iron-binding proteins (LTF, SLC40A1, CYP4Z1 and CYP4Z2P) previously linked to breast cancer." (PMID 21209903, 2010). "Of these genes, PTK7, KLK6 and LIMCH1 have interesting links with breast cancer; PTK7 is a catalytically inactive receptor tyrosine kinase in the Wnt signalling pathway, and a PTK7 targeted antibody–drug conjugate has been shown to reduce tumour-initiating cells." (PMID 38036593, 2023).
lung carcinoma (3 papers, 2021 to 2023). "We further investigated whether miR-660-5p promoted proliferation and metastasis of lung cancer cells via LIMCH1, SMARCA5, and TPP2." (PMID 38057344, 2023). "LIMCH1 is responsible for cell motility based on actin cytoskeleton remodeling, and plays a negative role in growth of lung cancer." (PMID 38057344, 2023).
renal carcinoma (3 papers, 2018 to 2022). A carcinoma arising from the epithelium of the renal parenchyma or the renal pelvis. "According to survival analysis of the Human Protein Atlas, LIMCH1 is also a prognostic gene, whose high expression is associated with favorable outcomes in renal cancer." (PMID 35565241, 2022).
breast tumor (1 paper, 2020). "Because NUP93 silenced cells did not significantly contribute to breast tumor formation and propagation in vivo, we then hypothesized that the level of Nup93 and other proteins directly regulated by Nup93 (e.g., LIMCH1) could be correlated with the progression of the disease in patients." (PMID 31959624, 2020).
Huntington disease (1 paper, 2021). Huntington disease (HD) is a rare neurodegenerative disorder of the central nervous system characterized by unwanted choreatic movements, behavioral and psychiatric disturbances and dementia. "LIMCH1 has been reported as a non-muscle myosin regulator and has been associated with Huntington’s disease with little other characterization, including, to our knowledge, no reports of regulated splicing." (PMID 34515025, 2021).
lymph node metastasis (1 paper, 2023). "Compared to the samples without lymph node metastasis, ADRB2, DPYSL2, LIMCH1, and PIK3R1 were downregulated in samples with lymph node metastasis." (PMID 38057344, 2023).
myotonic dystrophy type 1 (1 paper, 2023). Steinert disease, also known as myotonic dystrophy type 1, is a muscle disease characterized by myotonia and by multiorgan damage that combines various degrees of muscle weakness, arrhythmia and/or cardiac conduction disorders, cataract, endocrine damage, sleep disorders and baldness. "In addition, LIMCH1 is mis-spliced in myotonic dystrophy type 1, with the muscleblind-like (MBNL) family of proteins acting as the likely major regulator of Limch1 alternative splicing in skeletal muscle." (PMID 36977593, 2023).
neurogenic muscular atrophy (1 paper, 2025). "A study examining myofibers affected by neurogenic muscular atrophy revealed the overexpression of 55 proteins found that most of them, including LIMCH1 were involved in myofibrillogenesis." (PMID 40563874, 2025).
ovarian carcinoma (1 paper, 2022). A malignant neoplasm originating from the surface ovarian epithelium. "Although LIMCH1, CRLS1, CDT1, CNIH4 have been associated with various cancers, their relationship with ovarian cancer has been proposed in this study for the first time to the best of our knowledge." (PMID 36338962, 2022). "However, the association of LIMCH1 with ovarian cancer has not been identified yet." (PMID 36338962, 2022). "As a result, six genes (CDT1, CNIH4, CRLS1, LIMCH1, POC1A, and SNX13), and two miRNAs (mir-147a, and mir-103a-3p) were suggested as novel candidate prognostic biomarkers for ovarian cancer." (PMID 36338962, 2022). "Furthermore, LIMCH1, CRLS1, CDT1, and CNIH4 were found to be associated with various cancer types, but their roles in ovarian cancer have not been identified yet." (PMID 36338962, 2022).
salivary gland tumors (1 paper, 2017). "miR-21 and miR-30e may have a critical role in salivary gland tumor development with targeting RPS7 and LIMCH1 genes." (PMID 27184509, 2017).
tumor (10 papers, 2015 to 2025). "IHC results in our LUAD cohort demonstrated that the LIMCH1 expression level was significantly associated with pleural invasion, tumor length, tumor differentiation grade, and clinical tumor stage." (PMID 33391414, 2021). "Our results show that reduced LIMCH1 expression is associated with pleural invasion, more substantial tumor length, lower differentiation grade, and more advanced tumor stage." (PMID 33391414, 2021). "The six key-gene signature (ADRB2, DPYSL2, IL7R, LIMCH1, PIK3R1 and SOX2) has been shown to be associated with metastasis and progression of many tumor types through molecular experiments." (PMID 38057344, 2023). "Lower LIMCH1 expression positively correlated with several parameters, including pleural invasion, tumor length, tumor differentiation grade, clinical tumor stage and therapeutic strategy (all P<0.05)." (PMID 33391414, 2021). "Among them, hsa_circ_0069244 (circLDB2) can served as a ceRNA to induce LIMCH1 expression to suppress the development of tumor and promote cisplatin sensitivity in LUAD by binding to miR-346." (PMID 34801043, 2021). "Loss of Nup93 led to significant defects in tumor establishment/propagation in vivo, whereas patient samples revealed that high Nup93 and low LIMCH1 expression correlate with late tumor stage." (PMID 31959624, 2020). "Filtering yielded 46 likely somatic mutations in the tumor, of which 7 (affecting EIF4A1, EPHA3, FAF1, IPO8, KIAA1377, LIMCH1, and NIPBL) were confirmed in the RNASeq results." (PMID 25861239, 2015). "We found that LIMCH1 plays a role in tumorigenesis and tumor progression." (PMID 33391414, 2021). "Comparison of LIMCH1 expression with established clinicopathological markers revealed that LIMCH1high tumours were associated with non-squamous histological type (p = 0.05) and high tumour grade (p = 0.01)." (PMID 33723390, 2021). "Furthermore, the expression levels of miR-802, LIMCH1, and Rnd3 were assessed in A549 cells and mice flank tumor tissues." (PMID 27144337, 2016).
cancer (7 papers, 2010 to 2023). A tumor composed of atypical neoplastic, often pleomorphic cells that invade other tissues. "Due to its role in cell migration and adhesion, LIMCH1 has been associated with worse prognosis in multiple forms of cancer." (PMID 36474270, 2022). "LIMCH1 appears to be a novel prognostic target for LUAD, but more real-world studies are needed to confirm the critical mechanisms underlying cancer development in patients with LUAD." (PMID 33391414, 2021). "Among the genes encoding zinc ion-binding proteins, three (ANPEP, LIMCH1 and NR2F2) are known to be cancer-related." (PMID 21209903, 2010). "In CPTAC-ccRCC, the protein expression of genes AR, GNB3, HHLA2, LIMCH1, and SAA1 had statistical significance in some comparisons of normal samples and cancer stage (Figure A9a–e)." (PMID 35565241, 2022).
LIMCH1 also shares sentences with these, for which no sentence is quoted: lung adenocarcinoma (2 papers); atherosclerosis (1); breast adenocarcinoma (1); chronic myelogenous leukemia (1); clear cell renal cell carcinoma (1); coronary artery disease (1); endometrial cancer (1); kidney cancer (1); myopia (1); neuropathy (1); non-small cell lung carcinoma (1); preeclampsia (1); skin melanoma (1).